ADRA1D (adrenoceptor alpha 1D)
Description:
Alpha-1 adrenergic receptors are G protein-coupled receptors for catecholamines that signal through the G(q) family of G proteins, including G(q) and G(11). Upon activation, they stimulate the phosphatidylinositol-calcium second messenger pathway, leading to calcium release from intracellular stores and activation of protein kinase C. ADRA1D binds the catecholamine ligands norepinephrine and epinephrine.
Synonyms: ADRA1A; ADRA1R; ADRA1; ALPHA1; DAR; dJ779E11.2
Tractability: Small molecule: an approved drug acts on it; a high-quality ligand is known; it belongs to a druggable protein family. Antibody: its Gene Ontology location is reachable by antibodies, with high confidence; UniProt places it where antibodies can reach, with medium confidence; UniProt predicts a signal peptide or a membrane-spanning region. PROTAC: a small molecule that binds it is known. Other modalities: an approved drug acts on it.
Target class: Small molecule receptor (family A GPCR); Adrenergic receptor; Monoamine receptor; Membrane receptor; Family A G protein-coupled receptor
Chemical probes: (R)-9s (high quality), CHEMBL56438, TERAZOSIN
Gene: Protein-coding gene on chromosome 20 (4,220,630 to 4,249,287, reverse strand). Ensembl gene ENSG00000171873.
Subcellular location: Cell membrane
Pathways (Reactome):
Signal Transduction: Adrenoceptors; G alpha (12/13) signalling events; G alpha (q) signalling events
Gene Ontology:
Molecular function: alpha1-adrenergic receptor activity; identical protein binding; protein binding; adrenergic receptor activity; G protein-coupled receptor activity
Biological process: adenylate cyclase-activating adrenergic receptor signaling pathway; adenylate cyclase-modulating G protein-coupled receptor signaling pathway; cell-cell signaling; G protein-coupled receptor signaling pathway; neuron-glial cell signaling; phospholipase C-activating G protein-coupled receptor signaling pathway; positive regulation of cell population proliferation; positive regulation of cytosolic calcium ion concentration; positive regulation of MAPK cascade; positive regulation of vasoconstriction
Cellular component: plasma membrane; membrane
Genetic constraint (gnomAD): Loss-of-function variants: 23 observed, 17.99 expected, observed/expected ratio (o/e) 1.28, 90% interval 0.92 to 1.77. The upper end of that interval is the gene's LOEUF score, 1.77, which puts it in group 6 of 6, group 1 being the genes least tolerant of losing a copy. Missense variants: 825 observed, 744.81 expected, observed/expected ratio (o/e) 1.11, 90% interval 1.04 to 1.17. Synonymous variants: 366 observed, 334.37 expected, observed/expected ratio (o/e) 1.09, 90% interval 1 to 1.19.
Homologues: Orthologues: chimpanzee ADRA1D (98% identical), macaque ADRA1D (98% identical), dog ADRA1D (91% identical), pig ADRA1D (87% identical), rat Adra1d (86% identical), mouse Adra1d (85% identical), rabbit ADRA1D (80% identical), guinea pig ADRA1D (77% identical), tropical clawed frog adra1d (53% identical), zebrafish adra1d (51% identical), Caenorhabditis elegans ser-5 (20% identical). Paralogues in human: ADRA1B (44% identical), ADRA1A (37% identical), ADRB1 (24% identical), ADRB3 (23% identical), ADRB2 (22% identical), ADRA2B (21% identical), ADRA2C (21% identical), ADRA2A (21% identical), DRD2 (21% identical), GPR101 (17% identical), OR13F1 (10% identical), OR5T1 (10% identical), and 6 more.
Diseases named in the same sentence as ADRA1D in open-access papers:
ADRA1D is named in the same sentence as 25 diseases in open-access papers, as found by Europe PMC text mining. Sharing a sentence is not in itself a finding about the gene and the disease. The quoted sentences say what the papers report.
Hypertension (4 papers, 2012 to 2022). The presence of chronic increased pressure in the systemic arterial system. "Adra1d encodes an αAR protein responsible for regulating physiopathological responses mediated by NE and Epi, particularly in cardiovascular diseases, including hypertension." (PMID 36159491, 2022). "Of the three alpha 1 adrenergic receptor isoforms (ADRA1A, ADRA1B, ADRA1D), ADRA1B showed the strongest association with hypertension (Pgene<0.005), DBP (Pgene<0.02), and SBP (Pgene<0.02)." (PMID 22615923, 2012). "Similarly, some components of the SNS, such as Adra1d, appear to work in the direction to ameliorate hypertension." (PMID 34010951, 2021). "ADRA1D comes from the herb 丹参 (RADIX SALVIAE), which is effective on hypertension." (PMID 33106157, 2020).
Alzheimer disease (2 papers, 2020 to 2024). A progressive, neurodegenerative disease characterized by loss of function and death of nerve cells in several areas of the brain leading to loss of cognitive function such as memory and language. "The alpha-D1 adrenergic receptor encoded by ADRA1D is also downregulated in the hippocampus of Alzheimer’s disease and dementia with Lewy bodies patients, and noradrenergic impairment is present in PD patients as well." (PMID 32858884, 2020). "ADRA1D (α-1D adrenergic receptor), the target gene with which Guanabenz has been associated, aligns with recent discoveries showing the downregulation of the alpha-D1 adrenergic receptor encoded by ADRA1D in the hippocampus of patients with Alzheimer’s disease and dementia linked to Lewy bodies." (PMID 39273521, 2024).
Arrhythmia (2 papers, 2020 to 2021). Any cardiac rhythm other than the normal sinus rhythm. "The PPI k-means classification results suggested that 25 genes, iADORA1, ADORA2B, ADRA1A, ADRA1B, and ADRA1D, play a more important role in arrhythmia pathology and PRP treatment." (PMID 34393777, 2021).
colon cancer (2 papers, 2015 to 2018). "Of particular interest, three additional PDZ proteins—DLG1, CASK, and LIN7A—were detected in SW480 colon cancer cells, suggesting additional, yet to be characterized, ADRA1D complexes exist and are cell-type dependent." (PMID 26617989, 2015). "It is found that ADRA1D is differentially expressed in stage IV compared to stages II and III colon cancer." (PMID 30186855, 2018).
heart failure (2 papers, 2018 to 2019). Inability of the heart to pump blood at an adequate rate to meet tissue metabolic requirements. "There was also trends toward decreased transcription of KCa2.2 (Kcnn2) and increased transcription of adrenergic receptor subtype Adra1d, thought to protect against pathological remodeling in heart failure." (PMID 31068841, 2019).
cervical cancer (1 paper, 2022). A primary or metastatic malignant neoplasm involving the cervix. "The genes which were being termed as an essential marker for significant prognosis of cervical cancer were ADRA1D, LTBP2 whereas KLC2 protein-protein was termed for poor prognosis in early NsCLC patients." (PMID 35057823, 2022).
depression (1 paper, 2015). "However, in IBS patients only, when controlling for depression score the difference for the ADRA1D SNP rs1556832 on the volume of the left hippocampus was no longer significant." (PMID 26288143, 2015).
epilepsy (1 paper, 2025). A brain disorder characterized by episodes of abnormally increased neuronal discharge resulting in transient episodes of sensory or motor neurological dysfunction, or psychic dysfunction. "Meanwhile, the SMR analysis indicated a strong association between the expression of DRD4 and ADRA1D and epilepsy or its subtypes." (PMID 40170563, 2025). "SMR showed that DRD4 and ADRA1D were strongly associated with epilepsy or its subtypes however, neither gene passed the HEIDI test." (PMID 40170563, 2025).
glioma (1 paper, 2025). A benign or malignant brain and spinal cord tumor that arises from glial cells (astrocytes, oligodendrocytes, ependymal cells). "We sourced in the Gliovis dataset and we found that in the Chinese Glioma Genome Atlas (CGGA), the prognosis of patients with high ADRA1D gene expression was significantly worse than that of patients with low expression (p value=0.0066)." (PMID 40184918, 2025).
mild cognitive impairment (1 paper, 2022). "The results of the target-component network analysis showed that ADRB2, ADRA1B, DPP4, ACHE and ADRA1D played a key role in the treatment of mild cognitive impairment." (PMID 35646138, 2022).
pulmonary hypertension (1 paper, 2014). Increased pressure within the pulmonary circulation due to lung or heart disorder. "Further, several important regulators of systemic/pulmonary hypertension including ADRA1D, ECE1, and EDNRA were upregulated in HAPE." (PMID 24465776, 2014).
tumor (5 papers, 2013 to 2025). "This complements the Ivy-GFP data, which shows higher expression of ADRA1D gene and undifferentiated-related markers at the invasive tip and higher expression of differentiation-related markers at the tumor center." (PMID 40184918, 2025). "LAP3, ADRA1D, KIF25, GPS2, and MCF2L genes were associated with proliferation, movement, and invasion of tumor cells." (PMID 39839768, 2024). "To distinguish these tumors by the DNA methylation pattern more simply, we further selected four genes characteristically methylated among different tumor groups: ADRA1D, MGMT, VHL, and THBS1, and performed cluster analysis using the methylation average of 4 genes." (PMID 23638012, 2013). "Some data show that inhibition of the ADRA1D, MAPK and PI3K-Akt pathway leads to increased death in myoblast cells, suggesting a contribution of ADRA1D to tumor cell survival; however, we could not find previous data about its role in GBM." (PMID 33806345, 2021).
ADRA1D also shares sentences with these, for which no sentence is quoted: bladder pain syndrome (1 paper); cardiac hypertrophy (1); cardiovascular diseases (1); cavernous hemangioma (1); Chronic Obstructive Asthma (1); dementia (1); dementia with Lewy bodies (1); diabetic cardiomyopathy (1); insomnia (1); ischemia reperfusion injury (1); memory loss (1); metabolic syndrome (1); staphylococcus aureus infection (1).